RN7SL325P (RNA, 7SL, cytoplasmic 325, pseudogene)
Gene: Miscellaneous RNA gene on chromosome X (137,595,265 to 137,595,547, forward strand). Ensembl gene ENSG00000239579.
Homologues: Orthologues: chimpanzee Metazoa_SRP (100% identical), macaque Metazoa_SRP (87% identical). Paralogues in human: RN7SL1 (81% identical), RN7SL2 (81% identical), RN7SL126P (80% identical), RN7SL3 (80% identical), RN7SL113P (79% identical), RN7SL680P (78% identical), RN7SL230P (78% identical), RN7SL612P (78% identical), RN7SL732P (78% identical), RN7SL311P (78% identical), RN7SL566P (78% identical), RN7SL300P (77% identical), and 702 more.